TMEM88 (transmembrane protein 88)
Diseases named in the same sentence as TMEM88 in open-access papers (continued):
Sharing a sentence is not in itself a finding about the gene and the disease.
tumor (12 papers, 2015 to 2026). "In cancer, TMEM88 has been associated with a tumor suppressor and oncogenic function determined by its cellular location." (PMID 37936608, 2023). "Moreover, higher TMEM88 expression was associated with improved OS, further supporting its role as a tumor suppressor negatively regulated by miR-708." (PMID 41596760, 2026). "Apart from its role in tumor progression, TMEM88 has also been implicated in drug resistance." (PMID 37091140, 2023). "The increase in membrane-associated TMEM88 expression also led to a decrease of proliferation, colony formation, migration and invasion and to a decrease in tumor growth in vivo highlighting the tumor suppressor role of TMEM88 when it is localized to the membrane of the cell." (PMID 30574087, 2018). "Also, if miR-708-5p is repressing TMEM88 proteins equally, does loss of membrane-bound TMEM88 expression have a more/less profound effect on tumor cell phenotype?" (PMID 29050362, 2017). "Besides tumor progression, TMEM88 was also reported to be associated with drug resistance." (PMID 37091140, 2023). "At the level of isoform-specific protein expression—and, critically, the subsequent subcellular distribution—the correlation between TMEM88 and tumor progression or patient survival is dramatically reshaped." (PMID 41596760, 2026). "qRT-PCR validation of 201 tumor and 66 adjacent specimens confirmed underexpression of TMEM88 in cancerous tissue." (PMID 41596760, 2026). "One study specifically focused on how isoform-specific expression and localization of TMEM88 determine its functional impact on tumor progression." (PMID 41596760, 2026). "Taken together, our data suggested an anti-tumor effect of TMEM88 and verified its role as a novel prognostic biomarker in HCC." (PMID 37091140, 2023). "Tumor-related effects of TMEM88 in HCC were further validated through cellular and mice experiments." (PMID 37091140, 2023). "Among the analyzed tumor types, higher TMEM88 was only observed in HCC comparing with its paired liver tissues." (PMID 37091140, 2023). "We also overexpressed TMEM88 in the Huh7 human HCC cell line to investigate its tumor-related role in HCC." (PMID 37091140, 2023). "As a result, CCK-8 proliferation assay revealed an attenuated HCC growth after overexpressing TMEM88, highlighting the crucial role of TMEM88 as a novel tumor suppressor." (PMID 37091140, 2023). "To explore the possible tumor-related role of TMEM88, we firstly used in silico strategies to compare the mRNA level of TMEM88 in various tumors in TCGA datasets." (PMID 37091140, 2023). "Consistent with the growth curve, isolated xenografts established by TMEM88-overexpressing cells showed significant lighter tumor weight and smaller tumor size compared to those established by control cells." (PMID 37091140, 2023). "Since clinical evidence implied a potential tumor-suppressing role of TMEM88, we next conducted cellular experiments to validate its detailed effects in HCC." (PMID 37091140, 2023). "In these circumstances, exploring TMEM88 as a new biomarker for tumor diagnosis and confirming that TMEM88 has become a promising target will be the research and prevention of tumors." (PMID 35734592, 2022). "As an important tumor suppressor gene, TMEM88 benefits from the regulation of the Wnt signaling pathway and its downstream target genes and is widely involved in various biological events of malignant tumor cells, which has potential research value." (PMID 35734592, 2022). "But in the context of NSCLC, two different subcellular localizations for TMEM88 have been reported, suggesting different roles in tumor development depending on its localization." (PMID 30574087, 2018). "While membrane-bound TMEM88 is tumor suppressor by repressing WNT signaling, cytoplasmic localization is oncogenic and correlates with lower survival, metastasis, and late stage disease." (PMID 29050362, 2017).
tumor (continued). "By analyzing the correlations between TMEM88 levels with the immune cell enrichment, we observed that TMEM88 may be involved in the HCC tumor microenvironment." (PMID 37091140, 2023). "In any case, the results of multiple studies have shown that TMEM88 may be a tumor diagnosis and prognostic indicator, which will provide new clues and directions for the diagnosis and treatment of clinical malignant tumors." (PMID 35734592, 2022). "TMEM88 methylation affects tumor biology However, what is the specific mechanism?" (PMID 35734592, 2022). "In any case, as a two-transmembrane protein, TMEM88 has significant differences and specificities between multiple malignant tumor and adjacent tissues and tumor and normal cells, which makes TMEM88 a potential therapeutic target through different strategies during tumor treatment." (PMID 35734592, 2022). "However, the current research on TMEM88 is still in its infancy, and there is no complete summary to help researchers fully understand the important role of TMEM88 in tumor research and prevention." (PMID 35734592, 2022). "Furthermore, given the involvement of Wnt signaling in promoting resistance to various therapies, including cisplatin, docetaxel, and radiotherapy, TMEM88 may have broader implications in tumor treatment." (PMID 37091140, 2023). "Moreover, considering that Wnt signaling is involved in promoting resistance to cisplatin, docetaxel, radiotherapy, etc, it’s high likely that TMEM88 may help restore therapeutic sensitivity in tumors, highlighting its potential role in tumor treatment." (PMID 37091140, 2023). "Furthermore, it remains unclear whether the biological role of TMEM88 in tumor cells is dependent on its interaction with Dvl proteins." (PMID 26325443, 2015). "Among these genes, EFNA4 and TEDC2 were significantly upregulated, whereas CDC42EP2, STX11, THBD, TMEM88, and GPM6A were notably downregulated in tumor tissues compared with adjacent normal tissues." (PMID 42196266, 2026). "In the tumor microenvironment, the up-regulation of three TMEM genes (TMEM204, TMEM88, and TMEM59) in endothelial cells caught our attention." (PMID 37265785, 2023). "Therefore, more basic research needs to be carried out to further confirm the specific role of TMEM88 in tumor development, improve its credibility as a potential therapeutic target, and prove its potential to transform from basic research to clinical application in tumor treatment." (PMID 35734592, 2022). "Recently, a double-transmembrane protein named transmembrane protein 88 (TMEM88) was reported to regulate changes in downstream effectors by mediating different signaling pathways and was confirmed to be widely involved in cell proliferation, differentiation, apoptosis and tumor progression." (PMID 35734592, 2022). "Analysis of TCGA data revealed only weak positive correlations between TMEM88 mRNA and Wnt pathway genes (DVL1, FZD4 and 5, and ROR1), suggesting that the tumor-suppressive function of TMEM88 is largely independent of global Wnt signaling modulation." (PMID 41596760, 2026). "In this study, we observed a negative correlation between TMEM88 expression and unfavorable prognostic characteristics of HCC, including advanced tumor stage, poorer differentiation grade, and higher serum AFP level." (PMID 37091140, 2023).
cancer (8 papers, 2015 to 2025). A tumor composed of atypical neoplastic, often pleomorphic cells that invade other tissues. "In view of this, this review comprehensively describes the structure and function of TMEM88 and discusses its progress in the study of malignant tumors to provide important references and directions for subsequent research." (PMID 35734592, 2022). "Based on this, TMEM88 should be considered a novel and important research target in cancer research, which needs to be deeply explored for its potential." (PMID 35734592, 2022). "Specifically, TMEM88 has different expression levels in different tumors and has tissue specificity, but what are the specific characteristics; when there are multiple influencing factors, will the role of TMEM88 in malignant tumors be different?" (PMID 35734592, 2022). "In the process of cancer development, TMEM88 not only regulates the Wnt/β-catenin signaling pathway and participates in it but also affects other signal transduction processes." (PMID 35734592, 2022). "Meanwhile, co-immunoprecipitation and immunofluorescence analyses demonstrated that TMEM88 interacts with Dvl within the cytoplasm of cancer cells." (PMID 26325443, 2015). "Transmembrane protein 88 (TMEM88), a newly discovered protein that is localized on cell membranes, can inhibit the classical Wnt signaling pathway and is thought to have a bidirectional effect of inhibiting or promoting cancer in different contexts." (PMID 35126454, 2021). "Furthermore, TMEM88 can inhibit the Wnt/β-catenin–mediated in inflammatory and cancer." (PMID 35058782, 2021). "Therefore, we hypothesized that TMEM88 may modulate the prognosis of CRC by altering the sensitivity of cancer cells to chemotherapy through mediation of promoter methylation, although further investigation is needed to confirm this." (PMID 34184409, 2021). "Genes located above TRIM46 in the heatmap, such as ALOXE3, NR4A3, and TMEM88, did not exhibit similar upregulation in advanced-stage cancer tissues." (PMID 39937005, 2025). "TMEM88 expression was negative or low (final score < 3) in the normal tissues adjacent to the carcinomas." (PMID 26325443, 2015). "Although the downstream signaling pathway of TMEM88 in HCC was not explored here, it is high likely that TMEM88 functions through inhibiting Wnt/β-catenin signaling pathways as reported in various cancer types." (PMID 37091140, 2023).
adenocarcinoma (1 paper, 2017). A common cancer characterized by the presence of malignant glandular cells. "While the authors did not determine if TMEM88 expression was negatively correlated with miR-708-5p expression, they did show that high TMEM88 increased survival rates in adenocarcinomas of never smokers." (PMID 29050362, 2017).
TMEM88 also shares sentences with these, for which no sentence is quoted: cervical carcinoma (2 papers); gastric cancer (2); breast cancer in situ (1); carcinomas in situ (1); colon cancer (1); Hypertension (1); Non-Alcoholic Fatty Liver Disease (1); non-small cell lung carcinoma (1); prostate carcinoma (1); rectum cancer (1); uterine corpus endometrial carcinoma (1).